VDR (vitamin D receptor)
Diseases named in the same sentence as VDR in open-access papers (continued):
Sharing a sentence is not in itself a finding about the gene and the disease.
Hypercalcemia (continued). "Importantly, high 1,25D3 levels (hypervitaminosis D) lead to hypercalcemia, and shut down PTH production in the PTG via calcium-dependent but VDR-independent pathways." (PMID 33288743, 2020). "In contrast to 1α,25-dihydroxyvitamin D3 (1,25-D3 or calcitriol), a naturally occurring VDR agonist, VDR 4-1 therapy even at high doses did not induce hypercalcemia." (PMID 28814738, 2017). "Systemic inhibition of CYP24A1 can result in hypercalcemia and thus we sought to identify a CYP24A1 resistant VDR agonist, which could be given in sufficient quantities to reduce VCaP xenograft growth." (PMID 28591703, 2017). "In conclusion, we have identified a unique VDR agonist compound with beneficial effects in mouse models of hyperparathyroidism and heart failure without inducing significant hypercalcemia." (PMID 28814738, 2017). "A nonsecosteroidal VDR agonist, LG190119, has been shown previously to inhibit growth of LNCaP xenograft tumors in vivo without causing hypercalcemia." (PMID 28591703, 2017). "For example, it is known that high levels of calcitriol cause hypercalcemia, but research is being done to develop vitamin D analogues which are capable of being agonists to VDR while not producing hypercalcemia." (PMID 17678531, 2007). "Contrary to expectations, vitamin D supplementation did not reverse serum Ca2+ or 25(OH)D levels, nor restore intrarenal VDR activity, implying that sustained hypercalcemia may override the regulatory effects of vitamin D signaling." (PMID 40699786, 2025). "Notably, in addition to the liver, VDR is also widely distributed in other tissues, which reduces the amount of CAL reaching the target site and results in possible adverse effects, such as hypercalcemia." (PMID 37638336, 2023). "Thus, our results demonstrate that ZK does not fully abrogate VDR signaling in mice, but normalizes the expression of 1,25D3-induced target genes and hypercalcemia." (PMID 33288743, 2020). "The active form of vitamin D3, 1,25-dihydroxyvitamin D3 (D3), which acts through vitamin D receptor (VDR), is capable of inducing differentiation in myelo-monocytic precursor cells, but has been less widespread as a clinical treatment since D3 also induces hypercalcemia and hyperphosphatemia." (PMID 24922062, 2014). "There may also be important differences between paricalcitol, a selective vitamin D receptor agonist, and the nonselective calcitriol regarding PTH-lowering, risk of hypercalcemia and overall survival." (PMID 24930018, 2014). "In sharp contrast to vitamin D receptor activators, cinacalcet suppresses SHPT without inducing hypercalcemia or hyperphosphatemia." (PMID 29614098, 2018). "In this study, we have tested a novel nonsecosteroidal VDR agonist, VDRM2, which has a large safety margin against hypercalcemia and is not predicted to be a substrate for CYP24A1." (PMID 28591703, 2017). "Using the VCaP TMPRSS2:ERG positive cell line as a model, we found that a nonsecosteroidal CYP24A1 resistant VDR agonist, VDRM2, substantially reduces growth of xenograft tumors without inducing hypercalcemia." (PMID 28591703, 2017). "Using a virtual screening platform to search novel chemical probes that activate the vitamin D signaling, we report discovery of novel non-steroidal small-molecule compounds that activate the vitamin D receptor (VDR), but are devoid of hypercalcemia." (PMID 28814738, 2017). "An alternative approach is to utilize nonsecosteroidal VDR agonists that are not predicted to be substrates for CYP24A1 metabolism and show greater discrimination between levels required to induce a desired biological response and those that induce hypercalcemia." (PMID 28591703, 2017).
metabolic syndrome (51 papers, 2011 to 2025). A cluster of metabolic risk factors for CARDIOVASCULAR DISEASES and TYPE 2 DIABETES MELLITUS. "Although the relationship between vitamin D3 insufficiency and components of metabolic syndrome has been previously demonstrated, few studies have examined VDR gene polymorphisms for associations with the risk of these disorders." (PMID 38732523, 2024). "VDR of rs2228570 (FokI) has been proven associated with serious of chronic diseases, such as BP elevation and dyslipidemia, and even be served as the genetic marker for coronary artery disease." (PMID 37845735, 2023). "An important interaction between VDR gene polymorphisms and metabolic syndrome components was established." (PMID 37175993, 2023). "Many studies have uncovered a link between the VDR gene polymorphism and dyslipidemia, supporting this relationship." (PMID 35282461, 2022). "In this study, we demonstrate that paricalcitol, a vitamin D receptor activator, attenuates metabolic syndrome-associated cardiac dysfunction in rats." (PMID 35726330, 2022). "The VDR TaqI TT and BsmI BB + Bb genotypes were associated with lower 25(OH)D levels in the metabolic syndrome group." (PMID 32933052, 2020). "The goal of this study was to determine if vitamin D receptor (VDR) gene polymorphisms underlie susceptibility to dyslipidemia in a Chinese Han population." (PMID 30119682, 2018). "Three tag single nucleotide polymorphisms (SNPs) (rs11574129, rs2228570, and rs739837) were genotyped using TaqMan assays to determine VDR SNP associations with dyslipidemia." (PMID 30119682, 2018). "The aim of this study was to assess the relationship between vitamin D status and VDR gene polymorphisms with metabolic syndrome (MS) parameters in Russian middle-aged women." (PMID 30166978, 2018). "The purpose of this study was to investigate the association between metabolic syndrome (MetSyn) with the presence of VDR 2228570 C > T and VDR 1544410 A > G polymorphisms in Brazilian adults." (PMID 23855914, 2013). "The relationship between VDR BsmI and FokI polymorphisms and anthropometric and bio-chemical parameters describing metabolic syndrome were tested in 176 randomly selected men in Poland." (PMID 23049672, 2011). "We observed the influence of VDR FokI variants on dyslipidemia, oxidative stress, and BMI." (PMID 41020561, 2025). "However, the possible effect of VDR modulation on myocardial mitochondrial dynamics in metabolic syndrome-associated cardiac failure requires investigation." (PMID 35726330, 2022). "Emerging evidence indicates that variations in the VDR polymorphisms may contribute to dyslipidemia." (PMID 30975133, 2019). "The variation in rs2228750 reduced the stability of VDR and changed the binding energy of its ligand, which may be the underlying molecular mechanism for variant associated dyslipidemia." (PMID 30119682, 2018). "The VDR rs2228570 variant may increase susceptibility to dyslipidemia in the Chinese Han population." (PMID 30119682, 2018). "Hence, further studies on VDR polymorphisms would improve the understanding of the association of VDR with dyslipidemia." (PMID 30119682, 2018). "In addition to associations related to the vitamin D receptor gene and BsmI genotypes with glycemic markers, low serum concentrations of 25OHD3 have been associated with reduced insulin sensitivity, impaired glucose metabolism, and metabolic syndrome." (PMID 35213542, 2022). "Interestingly, a recent meta-analysis provided evidence of an association between VDR BsmI polymorphism and metabolic syndrome, supporting the idea that the VDR BsmI variant G allele may be a susceptibility marker of metabolic syndrome." (PMID 32407388, 2020). "Additionally, the results of a meta-analysis study by Han and co-workers suggested that VDR BsmI variant G allele might be a susceptibility marker of metabolic syndrome and VDR TaqI variant C allele might be a susceptibility marker of PCOS." (PMID 33134800, 2020).
metabolic syndrome (continued). "A growing body of research using human and animal disease model samples has shown that VDR is a metabolic gene and that individuals with metabolic syndrome and vascular diseases tend to have downregulated VDR expression." (PMID 38318147, 2024). "Other proposed mechanisms include high expressions of the vitamin D receptor in adipose tissue and the possibility of vitamin D playing a role in the pathogenesis of the metabolic syndrome." (PMID 37895163, 2023). "The Bsm variant of the VDR gene was associated with hypertriglyceridemia and may be predisposed to metabolic syndrome (MetS)." (PMID 32933052, 2020). "Considering the lack of studies evaluating the link between VDR and dyslipidemia, we investigated and determined the association between VDR variants and dyslipidemia in a large Chinese Han sample." (PMID 30119682, 2018). "If Sp1, Sp3, NF-kappaB, and VDR are increased in obese and T2D subjects, then this could be a mechanism underlying the elevated expression of ADAM19 in the metabolic syndrome." (PMID 28265178, 2017). "The absence of dyslipidemia in these animals does not foster plaque growth, thus providing insights on proatherogenic mediators specifically associated with VDR deletion, without the direct effects of the proatherosclerotic (apoE-/-) genotype." (PMID 26322890, 2015). "Hence, VDR gene may influence the progression of adiposity activity via dyslipidemia." (PMID 30975133, 2019). "Other proposed mechanisms are high expression of the vitamin D receptor (VDR) in adipose tissue and vitamin D possibly playing a role in the pathogenesis of the metabolic syndrome." (PMID 25681052, 2015). "Among the genes with the strongest relationship with metabolic syndrome, CNR1—cannabinoid receptor 1 gene, LEP—leptin promoter gene, FTO—alpha-ketoglutarate-dependent dioxygenase gene, MC4R—melanocortin 4 receptor gene and VDR—vitamin D receptor stand out." (PMID 32272684, 2020).
pancreatic cancer (48 papers, 2011 to 2025). "Amongstage IIa/IIb pancreatic cancer patients, VDR mRNA enrichment wasstrongly associated with increased mortalities (data not shown)." (PMID 35404047, 2022). "Stromal VDR activation reduces tumor-associated fibrosis and inhibits tumor-supportive signaling events in pancreatic cancer." (PMID 33614641, 2021). "In this study, two independent genomic screens of germline DNA variation in advanced pancreatic cancer patients selected VDR as a novel gene associated with patient survival." (PMID 30107003, 2018). "In a recent genome-wide association study of the overall survival of patients with pancreatic cancer, VDR gene polymorphism was associated with several prognostic factors." (PMID 24011168, 2013). "A few SNPs in the vitamin D receptor gene were associated with pancreas cancer risk; however, all were borderline significant." (PMID 23826131, 2013). "Interestingly, single nucleotide polymorphisms in the VDR gene are associated with a higher risk for pancreatic cancer." (PMID 25090635, 2014). "The expression of the vitamin D receptor (VDR) and its polymorphisms modulate the activity of vitamin D, which may in turn affect the prognosis of patients with pancreatic cancer." (PMID 24011168, 2013). "VDR is the natural receptor for 1α,25-dihydroxyvitamin D3 and its activation is associated with chromatin remodeling and is also proposed to increase the risk of esophageal squamous, prostate, and pancreatic cancers." (PMID 21980345, 2011). "Primary tumor tissue was unavailable from the patients in these studies, thus we were limited in our ability to determine whether this variant might increase VDR expression in pancreatic cancer cells, stromal cells, or other cellular components of the tumor microenvironment." (PMID 30107003, 2018). "Polymorphisms of the vitamin D receptor (VDR) gene may be a risk factor for pancreatic cancer (PC)." (PMID 23761840, 2013). "Overnight incubation with gemcitabine has been shown to upregulate VDR in PANC-1 pancreatic cancer cells." (PMID 41282147, 2025). "Another study reported that high expression of VDR in pancreatic cancer promotes M2 macrophage polarization and recruitment through the secretion of CCL20, which activates tumor progression." (PMID 40453717, 2025). "For the first time, we demonstrated in human pancreatic cancer the induction of VDR and we revealed that the upregulation of VDR mediated the feedback mechanism via which vitamin D can counteract the EMT induced by TGF beta." (PMID 34208208, 2021). "For this purpose, in the present study, we investigated two human pancreatic cancer cell lines and we found them sensitive to the TGFβ–VDR interplay, corroborating the relevance of these signaling pathways in tumor prevention." (PMID 34208208, 2021). "More recently, it was shown that vitamin D receptor (VDR) is present in the stroma of human pancreatic tumors, and its ligand, calcipotriol, reduces markers of inflammation and fibrosis in mouse models of pancreatitis and pancreatic cancer." (PMID 32116785, 2020). "Vitamin D receptor (VDR) is expressed in the stroma of pancreatic tumors and mediates interstitial reprogramming to inhibit pancreatitis and pancreatic cancer." (PMID 33226370, 2020). "The interplay among VDR rs2853564, drug treatment, and vitamin D supply should be investigated in pancreatic cancer patients in the context of clinical trials of vitamin D or its analogs combined with chemotherapy." (PMID 30107003, 2018). "Together, the clinical, genetic, and experimental results from this study point toward genetic variation in VDR as a novel determinant of the outcome of pancreatic cancer patients treated with chemotherapy." (PMID 30107003, 2018). "The Evans research group has analyzed the effect of the VDR on PSCs and potential impact of VDR-mediated stromal remodeling in the treatment of pancreatic cancer." (PMID 30400571, 2018).
pancreatic cancer (continued). "It has been shown that the activation of VDR by one of its ligands in a pancreatic tumor murine model resulted in reduced tumor fibrotic content, improved vasculature, and increased delivery of gemcitabine, with improved therapeutic efficacy." (PMID 30107003, 2018). "In the present study, the results of two genomic screens of germline DNA variation led to the investigation of VDR as a potential genetic determinant of the survival of pancreatic cancer patients." (PMID 30107003, 2018). "Similar conclusions on the role of VDR expression as a prognostic marker have already been addressed in pancreatic cancer and gastric cancer." (PMID 28632174, 2017). "Vitamin D receptor (VDR) is expressed in stroma from human pancreatic tumors and that treatment with the VDR ligand calcipotriol markedly reduced markers of inflammation and fibrosis in pancreatitis and human tumor stroma." (PMID 27655706, 2016). "The up-regulation of VDR in pancreatic cancer cells compared with normal cells has been shown in vitro in primary tumor cells, supporting our present results on mRNA level." (PMID 25090635, 2014). "Further prospective investigations should be conducted to study vitamin D supplementation for patients with pancreatic cancer and to determine the prognostic value of vitamin D levels and VDR expression in this patient population." (PMID 24011168, 2013). "For example, a ligand for VDR, calcipotriol, can decrease the levels of inflammation in the pancreas cancer tissue, suggesting that VDR could satisfactorily reduce tumor volumes with improved survival rates." (PMID 40296902, 2025). "In addition, certain SNPs within the genes of proteins involved in vitamin D metabolism (VDR, VDBP, and hydroxylases) have been shown to correlate with pancreatic cancer risk." (PMID 39850424, 2025). "The activation of VDR signaling enhances pancreatic cancer therapy." (PMID 38782891, 2024). "VDR is highly expressed in pancreatic cancer cells and pancreatic tumor stroma." (PMID 38782891, 2024). "Next, we aimed to examine whether MeTC7 can inhibit PD-L1 expression in a panel of diverse tumor cell types (AML, ovarian and pancreatic cancer) in vitro and in a syngeneic model that converges overexpression of both VDR/PD-L1 under the same settings." (PMID 37444542, 2023). "Treatment approaches that transdifferentiate activated CAFs into this quiescent phenotype include all-trans retinoic acid (ATRA), minnelide and the vitamin D receptor agonist calcipotriol, which facilitate resolution of liver and pancreatic fibrosis and enhance pancreatic cancer therapy." (PMID 36835352, 2023). "In addition, the synthetic analogues of vitamin D activate the VDR activator to arrest the pancreatic cancer cell cycle at G1 by downregulating expression of both β-catenin and AKT." (PMID 37561808, 2023). "Indeed, Sherman and colleagues reported the ability of calcipotriol, a synthetic form of calcitriol and a ligand of the vitamin D receptor (VDR) expressed on pancreatic tumor cells, to reduce the expression of markers of fibrosis and inflammation." (PMID 35892828, 2022). "A good example of normalizing CAFs is targeting the vitamin D receptor in pancreatic cancer." (PMID 33614646, 2021). "Another study has shown that VDR is expressed in the stroma in human pancreatic cancer." (PMID 32900990, 2020). "Our findings propose VDR as a novel determinant of survival in advanced pancreatic cancer patients." (PMID 30107003, 2018). "Due to the observed beneficial effects of endogenous levels of vitamin D for survival in pancreatic cancer, we hypothesized that both the VDR genotype status and levels of baseline vitamin D contribute to patient survival." (PMID 30107003, 2018). "Based upon the observed effect of rs2853564 in the luciferase assay, we tested whether rs2853564 might affect the mRNA expression of VDR in human pancreatic cancer tissues and cell lines." (PMID 30107003, 2018).